IDH1 (isocitrate dehydrogenase (NADP(+)) 1)
Diseases named in the same sentence as IDH1 in open-access papers (continued):
Sharing a sentence is not in itself a finding about the gene and the disease.
glioma (continued). "A mutation in IDH1/2 is considered as an early event in glioma-genesis." (PMID 35747806, 2022). "Therefore, we conducted a retrospective study to determine the prognostic usefulness of preoperative peripheral serum lymphocyte count, postoperative immunohistochemical index of IDH1 mutation status, and Ki-67 expression for glioma grading." (PMID 36147928, 2022). "It is well documented that IDH1-mutated gliomas arise from a distinct ‘cell of origin’." (PMID 36290819, 2022). "For example, IDH1 mutations have been associated with better outcomes in low‐grade gliomas." (PMID 35526267, 2022). "Importantly, these compounds exhibit equally satisfactory anti-proliferative activity against BT142 glioma cells with the R132H IDH1 mutation." (PMID 36091829, 2022). "Besides these 2-HG-mediated oncogenic effects, other metabolic changes were described in IDH1 mutated gliomas." (PMID 35628596, 2022). "Interestingly, a recent study demonstrated that ATRX loss promoted malignant and immunosuppressive phenotypes of IDH1 mutant glioma cells." (PMID 35720326, 2022). "Only 3 gliomas were mutated at R132H of IDH-1, and the rest were all IDH wild-type." (PMID 35756637, 2022). "On the one hand, this finding may be explained by the fact that epilepsy is associated with IDH1 mutations in low-grade gliomas, and IDH mutations predict better glioma prognosis." (PMID 36588901, 2022). "The mutation frequencies of IDH1 and ATRX in gliomas with a low-risk score were remarkably higher than in gliomas with a high-risk score (IDH1, 92% vs. 31%; ATRX, 33% vs. 21%), while TTN and MUC16 had lower mutation frequencies (TTN, 8% vs. 21%; MUC16, 7% vs. 10%)." (PMID 36311792, 2022). "Moreover, patients bearing gliomas with wild-type isoforms of IDH1 present a poorer prognosis when compared to patients with IDH1 mutated tumors." (PMID 35804976, 2022). "In addition, previous studies have reported that the biomolecular effect of glioma, including IDH1 mutation status, has a strong possibility of progressing to NCF decline in patients with glioma." (PMID 36347905, 2022). "However, clinical trial suggested that IDH1 mutation glioma patients appeared to be sensitive to conventional chemoradiation therapy." (PMID 35216362, 2022). "Comparisons I–III illustrate potentially novel metabolite profiles modulated by IDH1 mutation that might further explain different clinical features and prognoses of glioma subtypes." (PMID 34941573, 2022). "In glioma, the vast majority of mutations are found in IDH1 (90%)." (PMID 36286062, 2022). "For example, expressions of specific lncRNAs were specifically associated with the lower grade glioma (LGG) diagnostic genetic groups (classified by mutation in IDH1/2 genes and by 1p19q codeletion), and also with the classical, mesenchymal, neural, and proneural GBMs molecular subtypes." (PMID 35806337, 2022). "The authors screened 1010 glioma cases and found 743 cases with IDH1/2 mutations." (PMID 36286062, 2022). "Gliomas are known to have recurrent hotspot missense mutations in IDH1 and IDH2." (PMID 35806212, 2022). "Additionally, D2HG structurally resembles the excitatory neurotransmitter, glutamate, and D2HG in IDH1-mt gliomas have been associated with seizure incidence due to their agonistic actionon the NMDA receptor." (PMID 36643416, 2022). "TMEM158 is positively associated with glioma grade, IDH1 mutation status, and poor prognosis." (PMID 34992215, 2022).
glioma (continued). "Gliomas in orthotopic syngeneic glioma mouse models bearing the IDH1 mutation compared with gliomas in mice wild type (WT) for IDH1 also have reduced tumor-infiltrating cytotoxic T cells, as well as reduced chemokine CXCL10 expression and reduced STAT1-positive cells." (PMID 35385679, 2022). "The presence of an IDH1 gene mutation indicates that the GBM is a secondary low-grade glioma." (PMID 35045874, 2022). "Furthermore, IDH1/2 mutations have been predicted in clinical trials and retrospective analyses to improve the response to radiotherapy in low-grade gliomas, showing significantly prolonged progression-free survival and overall survival." (PMID 36358574, 2022). "Moreover, the vast majority of grade II/III gliomas and secondary glioblastomas (grade IV) are linked to better survival with mutations in IDH1 and IDH2 than wild type." (PMID 36497259, 2022). "Finally, the two groups were also significantly different at the level of somatic mutations, especially in glioma prognosis-related genes such as IDH1 and ATRX, with lower mutation rates in the high-risk group leading to poorer prognosis." (PMID 36226186, 2022). "Moreover, we found that the IDH1/2 mutational status evaluation helped establish RIG diagnosis in cases whose IDH1/2 mutational states differed between the primary and secondary glioma." (PMID 35505351, 2022). "In addition, we also observed that IDH1 mutation increases the misincorporated DNA 6mA in human gliomas, hinting that the misincorporated DNA 6mA can be erased in vivo." (PMID 35501312, 2022). "This study focused on redox metabolism as a treatment option in IDH1 mutated gliomas." (PMID 35628596, 2022). "In addition, glioma cells with IDH1 mutation demonstrate the activation of pyruvate carboxylase which leads to the increase in the formation of oxaloacetate products." (PMID 35625744, 2022). "The IDH1/2 mutations are a dividing point to categorize gliomas." (PMID 35804976, 2022). "EZH2 analysis might therefore be of clinical value for risk stratification, especially in patients with IDH1 R132H-negative gliomas." (PMID 36292072, 2022). "IDH1 mutations were previously shown to alter redox metabolism in glioma cells." (PMID 35628596, 2022). "Therefore, CXCL10 production is hampered in IDH1-mutated glioma cells in a STAT1-dependent manner, seemingly correlating with reduced tumor infiltration." (PMID 35385679, 2022). "Multidirectional changes in the activity of transketolase and hexokinase in the peritumoral zone of glial tumors were revealed in groups with a pronounced IDH1 mutation (significant increase) and with methylation of the MGMT gene promoter (significant decrease)." (PMID 35625744, 2022). "Whilst the most common IDH1 mutation in gliomas result in substitute of histidine for arginine, (IDH1 R132H), approximately 10% of mutations are at position 132, but may result in other amino acid substitution." (PMID 36286062, 2022). "In patients with IDH-mutant gliomas, investigators could detect tumor exosomes in the peripheral blood and analyze their cargo to successfully detect the IDH1-R132H mutation with a high concordance rate." (PMID 35740557, 2022). "We speculate that the mechanism of action of VASH1 in glioma may have some correlation with IDH1 and may provide a potential molecular marker for risk stratification of high-risk gliomas." (PMID 36504559, 2022). "Additionally, IDH1 mutation is sufficient to establish the glioma hypermethylator phenotype, which is a powerful determinant of tumor pathogenicity." (PMID 36276136, 2022).
glioma (continued). "Notably, epigenetic modifiers frequently showed more mutations in AYAs, including H3F3A, KDM5A and IDH1/2 in glioma, EP300 in liver cancer, SMARCA4 in ovarian cancer, and MEN1 in pancreatic cancer." (PMID 36433963, 2022). "However, it has been reported that nearly all 1p/19q codeleted glioma has IDH1 mutation; therefore, such biomarkers can be represented by the gene expression of IDH1 in a mediate manner, although the mutation cannot be directly detected." (PMID 35453785, 2022). "We aimed to identify specific immune biomarkers for IDH1-mutation (IDH1mt) glioma." (PMID 36159801, 2022). "The results showed that IDH1 mutation was dominant in glioma compared with IDH2." (PMID 35982398, 2022). "Although this study reveals some traditional factors that appear prognostically important in AYA glioma, most, including tumor grade, pathological subtype and genetic mutations such as IDH1/2, need to be considered with care given bias from the inclusion of older adults in many studies." (PMID 36479061, 2022). "Moreover, recurrent CIC mutations are found in gliomas (exclusively in those possessing an IDH1/2 mutation), implicating CIC as a potential tumour suppressor in this cancer type." (PMID 34767259, 2022). "Besides, IDH1, associated with a good prognosis in glioma patients, was also observed in more mutations in low-risk patients." (PMID 36437961, 2022). "In addition to the associated reports on gut microbiome and intratumoral bacteria with glioma, some findings revealed that oral microbiota features and gene functions are associated with glioma malignancy and the IDH1 mutation." (PMID 36003766, 2022). "However, according to the multivariate cox regression analysis, the tumor stage and IDH1 status are the only covariates significantly associated with the OS of glioma patients." (PMID 36232448, 2022). "Interestingly, IDH1 occupied the top one positions in four cohorts, which modulated diverse tumor-associated biological processes in glioma." (PMID 35620284, 2022). "IDH1 mutation alters the neurogenic niche and promotes glioma formation." (PMID 35538578, 2022). "Moreover, IDH1 mutation has been found to act as oncogenic events through comprehensively modifying metabolism and methylation profiles to drive glioma development 21-24." (PMID 34987659, 2022). "In glioma patients, R132H-mutated IDH1 is spontaneously processed, and an immunodominant epitope in the p123-142 region of MHC class II molecules is presented to CD4+ T cells, inducing spontaneous mutation-specific TH1 polarization and generation of mutation-specific antibodies." (PMID 35769466, 2022). "The gain-of-function IDH1 mutation is one of the most frequently observed mutations in glioma." (PMID 35385679, 2022). "IDH1/2 mutations promote the development of various cancers, such as lymphoma and glioma; ivosidenib, which targets mutated IDH1, and enasidenib, which targets IDH2, were approved for marketing and use in the treatment of acute myeloid leukemia in 2017 and 2018, respectively." (PMID 36230492, 2022). "IDH1 mutations are present in 55% of WHO III gliomas and 6% of WHO IV." (PMID 35055109, 2022). "In addition, phase I studies of ivosidenib also showed clinical benefits in IDH1‐mutated advanced glioma and advanced mutant IDH1 chondrosarcoma." (PMID 36254250, 2022). "However, gliomas remain the only cancer in which the IDH1/2 mutation constitutes a specific feature representing a propitious prognostic marker." (PMID 35912242, 2022). "Generally, IDH1 mutation and 1p/19q codeletion has been known as prognostic biomarkers in glioma." (PMID 35453785, 2022). "In addition, the observed decrease of N‐acetyl aspartate (NAA) and the increase of choline (Cho) as well as myo‐inositol (mI) is also typical in IDH1‐mutated gliomas." (PMID 35344608, 2022). "2-HG may accumulate to horrifically high levels of 5–35 mmol/g in human glioma samples with IDH1/2 mutations, which is 100-fold higher than its normal level in the brain." (PMID 36188571, 2022).
glioma (continued). "Similarly, an evaluation of cerebral microbleeds in gliomas has proved to be of significant value in predicting the glioma grade, IDH1 mutation, and MGMT methylation; this is affected by evaluating intratumoral susceptibility signal (ITSS) grades." (PMID 36289752, 2022). "Moreover, the authors discovered that MYD88 expression was higher in IDH1 wild types glioma and positively associated with M2 macrophage infiltration." (PMID 36248827, 2022). "Indeed, IDH1/2 mutations have been established as the most powerful positive prognostic factor for glioma patient survival, followed by age, tumor grade and MGMT gene methylation status." (PMID 35806153, 2022). "In addition to making tumour cells more sensitive to temozolomide and radiation therapy, IDH1 mutations can also make glioma cells susceptible to DNA damage and apoptosis." (PMID 36325335, 2022). "Various studies have reported spontaneous mutations in the NADP+-dependent IDH1 gene in glioma along with mutation in the IDH2 gene which is located on 15q26.1 chromosomal position with a frequent mutation at R172K (sometimes also at R172K, R172W, and R172M) of R172." (PMID 35873570, 2022). "However, by excluding the patients with isocitrate dehydrogenase 1 (IDH1) mutation, we found that all types of glioma patients displayed much lower DNA 6mA content compared to the normal tissues and no statistic difference in between." (PMID 35501312, 2022). "Mutation in IDH1 mostly affects Arg132 codon (R132), which is the binding site for isocitrate, and R132H is the most common alteration, comprising greater than 80% of all IDH1 mutations in gliomas." (PMID 35382567, 2022). "Moreover, it has been found to be epigenetically controlled by balance between IDH1/2 wild-type and mutation in human gliomas." (PMID 35931958, 2022). "These metaoboliets in turn accumulate in IDH1 or IDH2 mutated gliomas to millimolar concentrations." (PMID 35382567, 2022). "Of note, gliomas with isocitrate dehydrogenase 1/2 (IDH1/2) mutations display significantly lower NRF2 levels as compared to their IDH1/2 wildtype diffuse glioma counterparts; however, in the subclass of IDH-mutant gliomas, high NRF2 levels were associated with a worse clinical prognosis." (PMID 35892629, 2022). "As a result, in gliomas, the IDH1 mutation has an important role in hypermethylation." (PMID 35806212, 2022). "A statistically significant increase in the activity of this enzyme in the peritumoral zone in the event of an IDH1 mutation is consistent with the available data on the normalization of glucose metabolism in gliomas with an IDH1 mutation which leads to slower progression of the tumor." (PMID 35625744, 2022). "Preliminary phase I clinical data suggest that most of these IDH1 or 2 inhibitors are well tolerated, are associated with lower cellular 2-HG levels, and have potential antitumor activity, especially in IDH1-mutated gliomas." (PMID 35216362, 2022). "Additionally, a study indicated that IDH1-mutated glioma has elevated demands for glutathione to sustain malignancies." (PMID 35528238, 2022). "Moreover, some tumor types are characterized by mutations leading to widespread metabolic reprogramming (such as IDH1 mutations in glioma and inactivation of the von Hippel–Lindau tumor suppressor in kidney cancer)." (PMID 35565274, 2022). "Our cohort included 35 patients with IDH1-mutated grade three gliomas which have a better prognosis and may cause a potential bias." (PMID 36614997, 2022). "Moreover, lower DDR scores were observed in gliomas with IDH1 and ATRX mutations, but on the other hand, EGFR and PTEN mutations were associated with high DDR scores." (PMID 35720326, 2022). "In IDH-mutant gliomas, IDH1 and IDH2 mutations have typically shown mutual exclusivity." (PMID 36286062, 2022). "While unusual, the co-ocurrence of IDH1/2 mutations may deepen our understanding of their individual effects on glioma cell metabolism, and further studies into their clinical impact are needed." (PMID 36286062, 2022).
glioma (continued). "Thus, we suggest considering the IDH1 R132H mutation in enchondromas of patients with OD as a predictive risk factor of occurrence of glioma." (PMID 35884525, 2022). "In addition, we observed significant associations between glutamine metabolism and cell cycle processes, and CAD was significantly associated with prognosis in glioma patients with IDH1 mutations." (PMID 36568190, 2022). "Furthermore, only in three cases, our own included, molecular analysis was performed in both an enchondroma and glioma, and in all three cases (100%) the identical IDH1 R132H mutation was detected in both tumors." (PMID 35884525, 2022). "Moreover, the performance of these two techniques was evaluated in four patients with IDH1-mutated glioma." (PMID 34557149, 2021). "In the mouse platelet-derived growth factor (PDGF)-driven IDH1-mut and IDH1-wt gliomas, numbers of tumor-associated monocytes, macrophages, and polymorphonuclear leukocytes were significantly reduced, while numbers of microglia and CD4+ or CD8+ lymphocytes were not significantly changed." (PMID 33809675, 2021). "Glutamate dehydrogenase 2 (GLUD2) also could compensate to synthesize α-KG in IDH1mut gliomas, thereby resisting the growth inhibition caused by IDH1 mutation." (PMID 33472598, 2021). "When considering the potential combined anti-epileptic and anti-tumor activity of perampanel in glioma, it might be speculated that IDH1-mutated low-grade gliomas may benefit most in terms of reduction in seizure activity." (PMID 34068749, 2021). "Additionally, significantly higher PSMA staining vessel-counts were observed in WT compared to IDH1-R132H mutated gliomas (p < 0.001, WT: 13.3 vessels, IDH1-R132H mutated gliomas: 1.4 vessels)." (PMID 34209106, 2021). "ROC analysis of IVIM-DWI-derived parameters in gliomas grade and IDH1 mutation status was analyzed." (PMID 33795525, 2021). "Vorasidenib (AG-881) is a potent, oral, dual inhibitor of IDH1 and -2 mutations, and has been proven to penetrate the blood-brain barrier in several preclinical studies and inhibit 2-HG production in glioma tissue by more than 97% in an orthotopic glioma mouse model." (PMID 34360713, 2021). "IDH1 mutation status is a clinically effective molecular marker in glioma." (PMID 34123793, 2021). "In addition, we have previously demonstrated that the heterogenous 2-HG levels in 58 cases of IDH1-R132H mutated gliomas spanned from values close to 0–8.2 mM/g." (PMID 34079802, 2021). "It is conceivable that lower OEF and perfusion values in IDH1-mutated gliomas could be due to lower proliferation rates and less angiogenesis compared with their wild-type counterparts." (PMID 34671241, 2021). "Mutations in IDH1 or IDH2 are known to be drivers of tumorigenesis in both gliomas and AML." (PMID 34356864, 2021). "IDH1/2 mutation and chromosome 1p/19q codel are the two most common genetic changes in LGGs, representing driver events during glioma tumorigenesis, and are associated with better survival rates in glioma." (PMID 34335194, 2021). "The IDH1-R132H mutation is by far the most common IDH1 or IDH2 mutation observed in glioma." (PMID 33806933, 2021). "In gliomas, the frequency of IDH1 mutations in codon 132 increases in the order R132L, R132S, R132G, R132C, to R132H, with R132H constituting more than 90% of all IDH1 mutations." (PMID 34070746, 2021).